PDPN (podoplanin)
Diseases named in the same sentence as PDPN in open-access papers (continued):
Sharing a sentence is not in itself a finding about the gene and the disease.
pancreatic cancer (continued). "For example, bone marrow-derived macrophages (BMDMs) can express LYVE1, PROX1, and PDPN, and form lymphatic-like structures in vitro and LYVE1 + PROX1 + PDPN + bone marrow derived cells undergo lymphatic vascular mimicry during neo-lymphangiogenesis in VEGFC-expressing pancreatic tumors in mice." (PMID 38218743, 2024). "PDPN is one of the major surface markers for CAFs in pancreatic cancer." (PMID 37196797, 2023). "Similar to subcutaneous KPR tumours, development of LRRC15+PDPN+ CAFs in orthotopic pancreatic tumours was significantly impaired in Dptki/kiTgfbr2fl/fl mice compared with control Dptwt/wtTgfbr2fl/fl mice, whereas the total number of PDPN+CD31– fibroblasts remained unchanged." (PMID 36171287, 2022). "Indeed, pancreatic cancer cells and their microvesicles can express tissue factor, podoplanin, and thrombin on their membrane." (PMID 34589424, 2021). "PDPN expression in CAFs is correlated with shorter overall survival of pancreatic cancer patients." (PMID 33333727, 2020). "The PDPN-positive area in the pancreatic cancers ranged from 0.45 to 36.29% (median 11.83)." (PMID 28702871, 2018). "They found a 73% (16/22) positivity rate for PDPN expression in pancreatic cancer." (PMID 24354864, 2013). "Moreover, migration and invasion of pancreatic cancer cell lines (PANC-1 and SUIT-2) were associated with PDPN expression in CAFs (P < 0.01) and expression of CD10, matrix metalloproteinase (MMP) 2, and MMP3." (PMID 24354864, 2013). "Interestingly, PDPN-bearing microvesicles derived from tumour cells were observed in the circulation of patients with pancreatic and colorectal cancer, implying a possible prothrombotic role for PDPN in pancreatic cancer, also." (PMID 31327867, 2019). "Thus, PDPN expressed in stromal fibroblasts around pancreatic tumours might be involved in cancer progression and increased thrombotic risk, via mechanisms mediated by multiple growth factors derived from activated platelets." (PMID 31327867, 2019). "PDPN may become an important target of therapy for pancreatic cancer." (PMID 28702871, 2018). "Thus, as PDPN expression is involved in the prognosis of pancreatic cancer patients, it may be a useful marker to identify patients with a poor prognosis after surgery." (PMID 28702871, 2018). "When co-cultured with a variety of pancreatic cancer cell lines in Dulbecco’s modified Eagle’s medium (DMEM) / 2% fetal bovine serum (FBS), the populations of PDPN-expressing CAFs increased in a time-dependent manner, especially CAF4 on day 5, compared with CAF monocultures." (PMID 24354864, 2013). "Furthermore, DTR+ pancreatic tumours, whether treated with anti-PDL1 or isotype control, showed a near complete ablation of LRRC15+ CAFs and a significant reduction in the total PDPN+ fibroblast compartment." (PMID 36171287, 2022). "Although PDPN+ CAFs have not been studied in HGSOC, they have been associated with an immunosuppressive microenvironment and/or poor prognosis in multiple cancers, including breast, lung, esophageal, and pancreatic cancers." (PMID 36497028, 2022). "The pancreatic cancer cell line PANC-1 did not express PDPN mRNA." (PMID 24354864, 2013).
brain tumors (25 papers, 2012 to 2024). "High PDPN expression in primary brain tumors is associated with an increased risk of venous thromboembolism (VTE) cancer progressionand overall poor prognosis." (PMID 35814405, 2022). "Because of its ability to induce platelet aggregation, podoplanin was identified as a risk factor for coagulation and thrombosis in inflammatory processes (see Section 5) and cancer, mostly in patients with brain tumors and leukemias." (PMID 30736372, 2019). "Independent studies revealed that podoplanin expression in brain tumors is associated with increased VTE risk, whereas the isocitrate dehydrogenase 1 (IDH1) mutation is associated with very low VTE risk." (PMID 29676036, 2018). "Interestingly, high PDPN expression in primary brain tumors induces platelet aggregation and is associated with increased risk of VTE." (PMID 38067218, 2023). "However, in a previous study we identified that the high podoplanin expression of brain tumours is functionally linked with the increased VTE risks of this cancer type." (PMID 34066760, 2021). "Based on these observations, podoplanin‐induced platelet aggregation might be a major driver of brain tumor‐associated VTE." (PMID 29676036, 2018). "This shows that brain tumor patients with the IDH1 mutation are at a lower risk of VTE, while the risk in patients with IDH1 wild-type tumors is strongly linked to PDPN expression levels." (PMID 39682237, 2024). "Previous research suggests that the pathophysiology of VTE in brain cancer involves platelet activation through a molecule called podoplanin, which is frequently expressed by brain tumour cells." (PMID 38613361, 2024). "In various brain tumors, such as ependymal tumors, astrocytic tumors, and hemangioblastomas, PDPN overexpression has been observed." (PMID 38470096, 2024). "In particular, brain tumors can overexpress podoplanin, which is a transmembrane sialoglycoprotein and a potent activator of platelet aggregation." (PMID 38474013, 2024). "Podoplanin expression was determined by immunohistochemical staining of brain tumour tissue samples; these data were available from a previous study." (PMID 38613361, 2024). "Immunohistochemical staining for PDPN and intratumoral platelet aggregates was performed in brain tumor specimens from 213 brain cancer patients enrolled in the Vienna Cancer and Thrombosis study with a follow-up period of 2 years." (PMID 40741180, 2024). "With respect to brain tumors, the following question emerges: how can podoplanin expressed on the surface of tumor cells reach the bloodstream and trigger venous thromboembolism?" (PMID 30736372, 2019). "Although brain tumor patients with IDH1 mutation are at very low risk of VTE, the risk of VTE in patients with IDH1 wild‐type tumors is strongly linked to podoplanin expression levels." (PMID 29676036, 2018). "All brain tumors that expressed podoplanin to a medium‐high extent showed also an IDH1 wild‐type status." (PMID 29676036, 2018). "Importantly, the expression of PDPN and IDH1 mutation in primary brain tumors appeared to be mutually exclusive." (PMID 40741180, 2024). "Indeed, patients with podoplanin-positive brain tumours had significantly reduced platelet counts and increased risk of thromboembolism." (PMID 30745334, 2019). "Podoplanin has the ability to induce direct platelet activation via the platelet-receptor CLEC-2, and the role of podoplanin in cancer-associated thrombosis has been mainly reported for brain tumors." (PMID 31212608, 2019). "Taken together, brain tumor growth seemed to impact on peripheral T-cells and PDPN+ myeloid cells." (PMID 30972297, 2019). "Similar platelet activation and subsequent thrombus formation has been attributed to interactions between podoplanin-expressing perivascular cells and circulating platelets in murine models of deep vein thrombosis and Salmonella infection, and in patients with podoplanin-positive brain tumours." (PMID 30745334, 2019).
brain tumors (continued). "Patients with wild-type IDH1 brain tumors and high PDPN expression showed a significantly increased VTE risk compared with those with mutant IDH1 tumors and no PDPN expression." (PMID 39682237, 2024). "The results indicated a correlation between PDPN expression and IDH1 status in brain tumors." (PMID 39682237, 2024). "The potential of PDPN has been recognized as a therapeutic target of CAR T cells to treat brain tumors, and we previously generated a third generation of CAR that targeted PDPN using an anti-pan-PDPN antibody, NZ-1-based single-chain variable fragments (scFvs)." (PMID 35991754, 2022). "Patients with wild‐type IDH1 brain tumors and high podoplanin expression had a significantly increased VTE risk compared with those with mutant IDH1 tumors and no podoplanin expression (6‐month risk 18.2% vs. 0%)." (PMID 29676036, 2018). "Since increased intra-tumoral platelet aggregates correlate with VTE events in patients with brain cancer, it can be reasoned that platelets are caught by podoplanin of the brain tumour and related proteome changes are not detectable in peripheral blood platelets." (PMID 34066760, 2021).
oral squamous cell carcinoma (25 papers, 2007 to 2026). "Here, we demonstrated that a distinct cancer-associated fibroblasts subset with podoplanin (PDPN) positive expression (PDPN+ CAFs) was correlated with poor survival in oral squamous cell carcinoma (OSCC)." (PMID 37993428, 2023). "This study aims to determine association of SOX2 and podoplanin expression in the progression of oral squamous cell carcinomas and to elucidate the association between two proteins." (PMID 31508790, 2019). "The study shows that there is an association between SOX2 and podoplanin during the development and progression of oral squamous cell carcinomas." (PMID 31508790, 2019). "The purpose of this study is to determine the role of podoplanin as a biomarker for cancer risk assessment in oral leukoplakia and correlation of podoplanin expression with grades of oral squamous cell carcinoma (OSCC)." (PMID 26558136, 2015). "For cervix and oral squamous cell carcinoma, podoplanin is associated with migration/invasion, making it a novel prognostic marker for patients with these tumors." (PMID 22580922, 2012). "In relation to the possible role of podoplanin in tumour progression, it has been reported that high podoplanin expression significantly associates with nodal metastasis and reduced survival in oral squamous cell carcinomas." (PMID 20196862, 2010). "Podoplanin (PDPN), which plays an important role in cell adhesion, is associated with mortalin released by oral squamous cell carcinoma cells on their cell surface." (PMID 38646439, 2024). "Here, we found that podoplanin-positive cancer-associated fibroblasts (PDPN+ CAFs) is a distinct subtype of CAFs in tumor microenvironment and mediated the progression of oral squamous cell carcinoma (OSCC)." (PMID 37993428, 2023). "To investigate the expression of podoplanin (PDPN) in oral squamous cell carcinoma (OSCC) stroma, we analyzed the expression of PDPN in the stroma of 32 fresh human OSCC samples and corresponding adjacent normal tissues." (PMID 37993428, 2023). "PDPN upregulation potentiated invasion of low invasive oral squamous cell carcinoma cells by increasing the formation of invadopodia and the degradation of extracellular matrix." (PMID 36156321, 2023). "In oral squamous cell carcinoma, podoplanin (PDPN) is a transmembrane glycoprotein on the surface of tumor cells." (PMID 37719444, 2023). "Eighty-seven oral squamous cell carcinomas, in clinical stages I or II, arising in the tongue or floor of the mouth were stained with podoplanin." (PMID 33706734, 2021). "The immunohistochemical expression of SOX2 and podoplanin were evaluated in 60 cases of primary oral squamous cell carcinomas." (PMID 31508790, 2019). "Podoplanin expression is evident in the early phases of oral squamous cell carcinoma transformation and it has been able to distinguish dysplastic lesion that transformed to malignancy from those that did not progress." (PMID 31508790, 2019). "Few studies have analyzed the expression of SOX2 and podoplanin in the progression of oral squamous cell carcinomas." (PMID 31508790, 2019). "In this study the expression of podoplanin was evident in 45/60 (75%) cases of oral squamous cell carcinomas." (PMID 31508790, 2019). "This study aimed to evaluate the participation of moesin and podoplanin in the invasive tumor front of oral squamous cell carcinomas, and their influence on patients’ prognosis." (PMID 29310601, 2018). "The overall survival and the prognostic value of moesin and podoplanin expression in oral squamous cell carcinomas were analyzed in this study." (PMID 29310601, 2018). "The expression of podoplanin in oral squamous cell carcinomas was weak in 49 tumors and strong in 35 tumors." (PMID 29310601, 2018). "Initial studies about podoplanin related strong podoplanin expression to the worst prognosis and more advanced stages of oral squamous cell carcinomas." (PMID 29310601, 2018).
oral squamous cell carcinoma (continued). "Membranous and cytoplasmic podoplanin expression was observed in oral squamous cell carcinomas with a predominance of the membranous expression." (PMID 29310601, 2018). "In the past, podoplanin had been used often to assess intratumoral and peritumoral lymphovascular density in oral squamous cell carcinoma, which was correlated with metastatic spread to the lymph nodes and a poor prognosis." (PMID 29410757, 2017). "The aim of our study was to compare the expression of podoplanin in oral leukoplakia, oral submucous fibrosis and oral squamous cell carcinoma with that in normal buccal mucosa by immunohistochemical methods." (PMID 29410757, 2017). "Immunohistochemical expression of podoplanin was analyzed in 20 cases each of oral leukoplakia, oral submucous fibrosis, oral squamous cell carcinoma and normal buccal mucosa, with monoclonal antibody D2-40." (PMID 29410757, 2017). "There was a statistically significant upregulation of the grades of podoplanin expression in oral squamous cell carcinoma(100%), oral submucous fibrosis (90%) and oral leukoplakia (65%) when compared to that in normal mucosa(35%)." (PMID 29410757, 2017). "Podoplanin mRNA overexpression, in comparison to normal tissues, was also observed in some tumor tissues including colorectal cancer, oral squamous cell carcinoma or bladder cancer." (PMID 24797369, 2014). "Recent studies, however, have shown that podoplanin is also expressed in certain tumor cells, including many central nervous system, cervix, germinal and mesothelioma tumors, as well as oral squamous cell carcinoma." (PMID 22580922, 2012). "The expression of podoplanin was observed in 82% to 100% of cases of oral squamous cell carcinomas." (PMID 31508790, 2019). "Podoplanin and moesin immunoexpressions were evaluated by a semi-quantitative score method, based on the capture of 10 microscopic fields, at 400X magnification, in the invasive tumor front of oral squamous cell carcinomas." (PMID 29310601, 2018). "Overall analysis of podoplanin and moesin expression in oral squamous cell carcinomas was not statistically associated (p = 0.460)." (PMID 29310601, 2018). "Moreover, malignant cells of oral squamous cell carcinomas expressed both podoplanin and moesin, but these proteins probably act individually in tumor invasion process." (PMID 29310601, 2018). "Therefore, considering the latest controversial studies concerning podoplanin expression, we suggest that further studies with a larger sample should be conducted to confirm the potential prognostic value of this protein in oral squamous cell carcinomas." (PMID 29310601, 2018). "–15 This study aimed to correlate the combined expression of SOX2 and podoplanin with the clinicopathological features of oral squamous cell carcinoma, and thereby to determine their influence on the progression and clinical outcome of oral squamous cell carcinomas." (PMID 31508790, 2019). "Additionally, the weaker expression of podoplanin was associated with lymph node involvement and muscular infiltration in oral squamous cell carcinomas, indicating that podoplanin expression occurs in more differentiated cells and at earlier stages of the tumors." (PMID 29310601, 2018). "Previous studies have shown that PDPN expression correlated with LNM in numerous cancers, especially in early oral squamous cell carcinomas." (PMID 37158593, 2023). "Also, mtHSP70 interaction with podoplanin (PDPN) regulates the growth and invasion of oral squamous cell carcinoma." (PMID 36154922, 2022). "Interestingly, however, there is evidence that podoplanin can also promote single cell invasion of MDCK cells and human oral squamous cell carcinomas, thus contributing to EMT-mediated cell motility." (PMID 17179989, 2007).
lung squamous cell carcinoma (21 papers, 2007 to 2025). "In lung squamous cell carcinoma, CAFs expressing PDPN are linked with poor prognosis and tumor progression." (PMID 40741180, 2024). "PDPN encodes a type-I integral membrane glycoprotein, and its expression is upregulated in squamous cell carcinoma of lung." (PMID 31217907, 2019). "While this study investigated PDPN expression changes in gastric cancer cells causing activation in CAFs, other studies have shown that PDPN expression in CAFs themselves, results in poor prognosis of patients with lung squamous cell carcinoma as well as gastric cancer progression." (PMID 40741180, 2024). "In stage I lung squamous cell cancer, PDPN+ CAFs highly express TGF-β1 and are associated with the infiltration of CD204+ TAMs, further demonstrating that PDPN+ CAFs can lead to an immunosuppressive microenvironment." (PMID 37143134, 2023). "(2017) considered that the PDPN expression in CAFs was a marker of poor prognosis in patients with lung squamous cell carcinoma." (PMID 36156321, 2023). "PDPN antibody was identified to inhibit platelet aggregation and PDPN-induced lung metastasis in mouse model of lung squamous cell carcinoma." (PMID 35659308, 2022). "PDPN expression has significantly high correlations with better differentiation of squamous cell lung carcinoma (pooled OR = 2.64, 95% CI 1.53–4.56, P = 0.0005, fixed effect)." (PMID 32408907, 2020). "Podoplanin/Aggrus, known as a platelet aggregation-inducing factor, is frequently overexpressed in lung squamous cell carcinomas (LSCC) and glioblastomas among other tumours, and its expression has been reported to be correlated with poor prognosis." (PMID 28642617, 2017). "PDPN is overexpressed in 40% of lung squamous cell carcinomas." (PMID 35453596, 2022). "PDPN can be useful as a target molecule for lung squamous cell carcinoma." (PMID 35453596, 2022). "Knockdown of podoplanin suppressed tumor growth and metastasis of lung squamous cell carcinoma." (PMID 34722319, 2021). "PDPN+ CAFs also have an unfavorable prognostic value in lung squamous cell carcinoma." (PMID 33114328, 2020). "Podoplanin is also upregulated in squamous cell cancers of the lung." (PMID 17179989, 2007). "In addition, CLEC-2-podoplanin interaction could also modulate the proliferation of lung squamous cell carcinoma." (PMID 34722319, 2021). "We found PDPN to be abundantly expressed in mesothelioma, HNSCC, lung squamous cell carcinoma and testicular germ cell tumors." (PMID 33114328, 2020).